ZAR1L (zygote arrest 1 like)
Description:
mRNA-binding protein required for maternal mRNA storage, translation and degradation during oocyte maturation (By similarity). Probably promotes formation of some phase-separated membraneless compartment that stores maternal mRNAs in oocytes: acts by undergoing liquid-liquid phase separation upon binding to maternal mRNAs (By similarity). Binds to the 3'-UTR of maternal mRNAs, inhibiting their translation (By similarity).
Synonyms: Z3CXXC7; ZAR2
Tractability: No criterion of Open Targets' tractability assessment is met for any kind of drug.
Gene: Protein-coding gene on chromosome 13 (32,303,699 to 32,315,363, reverse strand). Ensembl gene ENSG00000189167.
Subcellular location: Cytoplasm, Cytoplasmic ribonucleoprotein granule
Subcellular location (Human Protein Atlas): Nucleoplasm; Nuclear speckles
Gene Ontology:
Molecular function: mRNA 3'-UTR binding; mRNA binding
Biological process: negative regulation of translation; oocyte maturation
Cellular component: cytoplasm; intracellular membraneless organelle; cytoplasmic ribonucleoprotein granule
Genetic constraint (gnomAD): Loss-of-function variants: 15 observed, 25.5 expected, observed/expected ratio (o/e) 0.59, 90% interval 0.39 to 0.91. The upper end of that interval is the gene's LOEUF score, 0.91, which puts it in group 3 of 6, group 1 being the genes least tolerant of losing a copy. Missense variants: 372 observed, 394.38 expected, observed/expected ratio (o/e) 0.94, 90% interval 0.87 to 1.03. Synonymous variants: 190 observed, 160.71 expected, observed/expected ratio (o/e) 1.18, 90% interval 1.05 to 1.33.
Homologues: Orthologues: chimpanzee ZAR1L (99% identical), macaque ZAR1L (94% identical), dog ZAR1L (76% identical), rabbit ZAR1L (75% identical), pig ZAR1L (74% identical), rat Zar1l (59% identical), mouse Zar1l (56% identical), tropical clawed frog zar1l (50% identical), zebrafish zar1l (45% identical), tropical clawed frog zar1l2 (41% identical). Paralogues in human: ZAR1 (41% identical).
Diseases named in the same sentence as ZAR1L in open-access papers:
ZAR1L is named in the same sentence as 4 diseases in open-access papers, as found by Europe PMC text mining. Sharing a sentence is not in itself a finding about the gene and the disease. The quoted sentences say what the papers report.
breast carcinoma (2 papers, 2010 to 2024). "Besides, ZAR1L has been suggested potential associated with tumor suppressors, which can repress the transcription of BACA2 to repress breast cancer cells." (PMID 38424222, 2024).
infertile (1 paper, 2024). "The underlying molecular mechanism and the role of Zar1l in oocyte meiotic maturation have been well characterized to only strengthen the Zar1 infertile phenotype in another study." (PMID 38786026, 2024).
lung carcinoma (1 paper, 2022). "In this study, we also investigated the correlations between 35 polymorphisms in 9 DNA repair genes (XRCC3, BRCA2/ZAR1L, XPC, RAD52, MAD2L2, NFKB1, NFKBIA, TNFRSF1A, and FASN) with platinum-based chemotherapy prognosis in 399 patients with lung cancer." (PMID 35899106, 2022).
ZAR1L also shares sentences with these, for which no sentence is quoted: tumor (2 papers).